CR1 (complement C3b/C4b receptor 1 (Knops blood group))
Diseases named in the same sentence as CR1 in open-access papers (continued):
Sharing a sentence is not in itself a finding about the gene and the disease.
systemic lupus erythematosus (20 papers, 2008 to 2025). An autoimmune multi-organ disease typically associated with vasculopathy and autoantibody production. "In systemic lupus erythematosus, a low CR1 density on neutrophils and other phagocytes causes excessive C3 activation, the release of proinflammatory cytokines, and immune-complex overload." (PMID 31824479, 2019). "In sum, we show that the minor allele at rs1876453 reduces risk of lupus and that this effect is due, in part, to increased expression of CR1 on B cells." (PMID 25180293, 2016). "Furthermore, it was associated with increased B cell expression of CR1, suggesting long-range effects of rs1876453 on gene regulation and providing a plausible mechanism by which it may alter lupus susceptibility." (PMID 25180293, 2016). "Reduced CR1 levels have been observed in patients with autoimmune diseases, such as systemic lupus erythematosus, rheumatoid arthritis, Sjögren’s syndrome, and paracoccidioidomycosis, potentially altering the binding site of the immune complex." (PMID 40149556, 2025). "Decreased ICs clearance can arise due to genetic polymorphisms and diverse expression of complement receptors on Mφs and erythrocytes, as seen with CR1 in systemic lupus erythematosus (SLE)." (PMID 39519159, 2024). "Decreased expression of CR1 protein was shown to occur in systemic lupus erythematosus, sarcoidosis, and AD." (PMID 37286172, 2023). "The density polymorphism is a stable phenotype that accounts for the constitutive expression level of CR1 on erythrocytes, although acquired deficiency may also occur in some diseases, such as systemic lupus erythematosus (SLE) and acquired immune deficiency syndrome (AIDS)." (PMID 30044434, 2018). "Likewise, cross-linking of BCR and CR1 was proven to lower the number of IgG anti-DNA producing plasma cells of lupus patients." (PMID 27981054, 2016). "Recently our studies found that reduced levels of erythrocyte CR1 may reflect disease activity in lupus patients by using specific monoclonal antibody CR1-2B11." (PMID 26273660, 2015). "Low erythroid CR1 levels have been correlated with gallbladder carcinomas, systemic lupus erythematosus (SLE), sarcoidosis, and Alzheimer’s disease." (PMID 37591894, 2023). "A role for complement receptors CR2 and CR1 in the autoimmune disease, Systemic Lupus Erythematosus (SLE) is well established." (PMID 35769482, 2022). "In systemic lupus erythematosus (SLE), the expression level of both CR1 on RBCs and CD21 on B cells is reduced." (PMID 22405566, 2012). "An increase in iC3b and other C3 fragments may contribute to complement-driven immune activation in diseases such as systemic lupus erythematosus (SLE) where patients have reduced levels of CR1 in erythrocytes." (PMID 35517827, 2022). "The ability of human CR1 to reduce autoimmunity has also been proven in humanized SCID mice transferred with PBMCs of lupus patients where cross-linking of the BCR and CR1 restored B cell tolerance and lowered the number of IgG anti-DNA producing plasma cells." (PMID 27981054, 2016). "The number of CR1 molecules decreases with aging of erythrocytes in normal individuals and is also decreased in pathological conditions such as systemic lupus erythematosus (SLE), HIV infection, some hemolytic anemias, and other conditions featuring immune complexes." (PMID 24278680, 2012).
autoimmune disease (18 papers, 2008 to 2025). A disorder resulting from loss of function or tissue destruction of an organ or multiple organs, arising from humoral or cellular immune responses of the individual to their own tissue constituents. "In conclusion, the findings reported here establish CR1 as a novel susceptibility gene for FSGS, involving an autoimmune disease component." (PMID 38076851, 2023). "CR1 plays a major role in inhibiting the complement system, removing immune complexes, and activating B cells, important events that are deregulated in autoimmune diseases." (PMID 31824479, 2019). "Expression of CR1 on B cells has been studied in a number of human autoimmune diseases and a significant reduction was found in CR1 density compared to control subjects." (PMID 27981054, 2016). "Our study supports the idea that genetic variations in C4, CR1, and CR3, associated with autoimmune disease susceptibility, could disrupt PGN recognition and promote systemic inflammatory conditions." (PMID 39656526, 2024). "CR1 and CLU gene are related to thymus function which could potentially cause an autoimmune disorder." (PMID 30666269, 2018). "The functions of CR1 and CR2 on T cells remain to be determined, but we note that CR2 is the receptor for Epstein-Barr virus, which is a cause of T cell lymphomas and a candidate environmental factor in autoimmune disease." (PMID 28814669, 2017). "A common CR1 C5507G single nucleotide polymorphism (SNP) in exon 33 has been shown to be associated with some diseases characterized by altered inflammatory response, and changes in CR1 expression have been shown in patients with a variety of inflammatory and autoimmune diseases." (PMID 21867543, 2011). "Among known classical complement receptors (CR), only type 1 complement receptor (CR1/CD35) was shown to bind both C4b and C3b fragments of cleaved C4 and C3 using two different domains for C4b and C3b, and this receptor is associated with the pathogenesis of certain autoimmune diseases." (PMID 37234916, 2023). "The two hub mRNAs, CR1 and TAP2, play important roles in the development of Sjögren’s syndrome and other autoimmune diseases while also contributing to COVID-19 progression." (PMID 40149556, 2025). "Finally, in certain autoimmune diseases such as SLE, C4, and CR1 were shown to play an important role." (PMID 37234916, 2023). "This suggests that the aberrant expression of CR1 contributes to initiation of autoimmune diseases rather than altering peripheral activation of the cells." (PMID 27981054, 2016). "We propose that mAbs 7D18.1 and 7D323.1 can act as surrogate markers for CR1 and CR2, respectively, and that they may be useful tools for studying the immune complexes that are generated in various autoimmune diseases." (PMID 21070093, 2011). "Thus, targeting the inhibitory CR1 and CR2 in autoreactive B cells could serve as a novel scenario for therapeutic options in autoimmune diseases." (PMID 39768874, 2024). "There is a growing body of evidence that CR1/CR2 plays an important role in maintaining and defining normal B cell function and thereby helps to prevent the onset of autoimmune disease (reviewed)." (PMID 19187965, 2009).
cognitive decline (13 papers, 2012 to 2025). "Complement receptor 1 (CR1) is one of the major AD risk factors associated with faster cognitive decline." (PMID 41272275, 2025). "The minor allele at rs6656401, associated with expression of the risk variant CR1*2, was linked to accelerated cognitive decline, reduced CR1 density on erythrocytes and increased sCR1 plasma levels." (PMID 37480051, 2023). "Recent studies have found associations of the CR1 SNPs rs6656401 and rs4844609 with AD and cognitive decline, although there is some controversy with respect to the association of memory decline with coding variant rs4844609, Ser1610Thr." (PMID 26914463, 2016). "For example, we showed that CR1, but not CLU and PICALM, was significantly associated with deposition of neuritic plaques, and this association further mediates, in part, the effect of the CR1 locus on cognitive decline [91•]." (PMID 23482655, 2013). "In a recent genome-wide scan, none of the known AD susceptibility variants, except APOE and CR1, were found to be significantly associated with the rate of cognitive decline [100•]." (PMID 23482655, 2013). "Moreover, it has been found that cognitive decline was linked with the CR1 rs6656401 SNP by using the established AD-associated genes." (PMID 29209239, 2017). "Given the roles that APOE e4 and CR1 AA/AG alleles have been reported to play in the deposition of β-amyloid, the breakdown of myelin and cognitive decline, the preponderance of these risk alleles may further suggest the presence of a survival effect among this cohort." (PMID 28344553, 2017). "Previous studies have shown that the effect of the APOE gene on the risk of cognitive decline and dementia was modified by other genetic factors, including ABCA7, SORL1, PICALM, CR1, BIN1, and TREM2, showing complex gene-gene interactions." (PMID 34214049, 2021). "We found that ABCA7, CD33, and CR1 expression levels were associated with clinical dementia rating (CDR), with higher expression being associated with more advanced cognitive decline." (PMID 23226438, 2012). "In contrast, a replication study indicated that the CR1 gene did not affect the risk of age-related cognitive decline in older Taiwanese adults." (PMID 29209239, 2017). "A subsequent replication study also indicated that the rs4844609 SNP in the CR1 gene modulates episodic memory decline and an interaction between APOE and CR1 influences cognitive decline for normal aging and for pathological aging." (PMID 29209239, 2017).
anaemia (12 papers, 2007 to 2025). "For example, a study on severe anaemia showed elevated surface IgG and immune complexes and deficiencies in the complement regulatory proteins CR1 and CD55." (PMID 36183114, 2022). "Consistent with this hypothesis, we have found that red cells of children with P. falciparum infection and severe anemia have acquired deficiencies in CR1 and CD55, and increased C3b deposition." (PMID 18717995, 2008). "Therefore, deposition of those immunocomplexes on the surface of nRBCs through the complement receptor 1 (CR1) could decrease nRBCs deformability thus predisposing them to clearance by phagocytes and contributing to anemia in vivax malaria." (PMID 29884876, 2018). "These cytokines cause bone marrow suppression and imbalance in red blood cell surface markers such as CR1, contributing to anaemia." (PMID 40406565, 2025). "There was evidence for reduced levels of CR1 on reticulocytes in infected individuals with mild anaemia in both falciparum and vivax malaria." (PMID 31533836, 2019). "In patients with severe anemia, the expression of CR1 on uninfected RBCs between P. vivax and P. falciparum was similar; however, the expression of CD55 in P. falciparum malaria was significantly lower than that in P. vivax malaria." (PMID 30429373, 2018). "During infection, the expression of complement receptor 1 (CR1) by monocytes/macrophages is down-regulated, leading to high levels of immune complexes such as those observed in patients with severe anaemia and cerebral malaria." (PMID 34271941, 2021). "Significant reductions of CR1 and CD55 have largely been reported in patients with severe anaemia from Plasmodium falciparum infection, and more recently from Plasmodium vivax infection." (PMID 31533836, 2019). "Expression of RBC CR1 and CD55 differed significantly among patients with different degrees of anemia." (PMID 30429373, 2018). "Other investigations have also implicated reduced anaemia (mild to moderate) in children with HbAS genotype relative to HbAA genotype and suggested that high levels of RBC complement regulatory proteins (CR1 and CD55) play a role in the pathogenesis of severe anaemia in malaria infection." (PMID 33827455, 2021). "The lowest expression of CR1 and CD55 was seen in patients with severe anemia." (PMID 30429373, 2018). "Levels of CR1 and CD55 were reduced in severe anemia in both falciparum and vivax malaria." (PMID 30429373, 2018).
dementia (10 papers, 2012 to 2025). Loss of intellectual abilities interfering with an individual's social and occupational functions. "Our ML approach identified expression of CR1 as a key factor in predicting fast versus slow progression to AD dementia, which is a novel finding of this study." (PMID 30783207, 2019). "The SNPs rs876461 (PRKD3; P = .02), rs117618017 (APH1B; P = .03), rs4844610 (CR1; P = .04), rs7584040 (BIN1; P = 2 × 10–3), rs11168036 (HBEGF; P = 8 × 10–3), rs143429938 (CLU/MIR6843; P = .04), and rs8064326 (KCTD2; P = 3 × 10‐4) were independently associated with incident dementia." (PMID 33532541, 2021). "Interestingly the CR1 rs3818361 variant appeared to be associated with premature mortality in our cohort, particularly in the subjects without dementia." (PMID 24438528, 2014). "Interestingly the CR1 rs3818361 variant appeared to be associated with mortality in our cohort, particularly in the subjects without dementia." (PMID 24438528, 2014).
Sepsis (9 papers, 2013 to 2024). Sepsis is defined as life-threatening organ dysfunction caused by a dysregulated host response to infection. "Our qPCR results and ROC curve analyses confirmed the accuracy of S100A8, S100A9, and CR1 in diagnosing sepsis as well as in predicting in-hospital mortality among patients with sepsis." (PMID 37298316, 2023). "And CR1 monoclonal antibody could ameliorate sepsis-induced mortality during Staphylococcus aureus infection." (PMID 33949285, 2021). "Key genes upregulated during sepsis, including S100A8, S100A9, and CR1, are responsible for cell cycle regulation and immune responses." (PMID 37298316, 2023). "In addition, we identified key genes that were upregulated in sepsis, namely, S100A8, S100A9, and CR1, as well as those that were downregulated, namely, CD79A, HLA-DQB2, PLD4, and CCR7." (PMID 37298316, 2023). "Thus, to functionally link the expression of these molecules to NOD2-mediated C5a generation during sepsis, CD55 and CR1/2 expression levels on gated peritoneal F4/80−Ly-6G+ neutrophils and F4/80+Ly-6G− macrophages were measured." (PMID 23675299, 2013). "Peritoneal F4/80+Ly-6G− macrophages minimally expressed CD55 and CR1/2 in WT and Nod2−/− mice with CLP, suggesting that expression modulation of these molecules on macrophages minimally contributes to NOD2-mediated C5a generation during sepsis." (PMID 23675299, 2013). "In addition, high PGN levels can promote a sepsis-like progression and interventions targeting PGN uptake, such as soluble CR1 competition or CR3 inhibition, may have therapeutic potential in managing severe inflammatory responses during bacterial infections." (PMID 39656526, 2024). "Notably, the key genes upregulated during sepsis are responsible for regulating cell cycle progression and differentiation (i.e., S100A8 and S100A9) and immune responses (i.e., ANXA1, APOBEC3A, LILRA5, CR1, and CD55)." (PMID 37298316, 2023).
viral infections (9 papers, 2006 to 2025). "Among viral infections, CR1 has been shown to be a secondary receptor for Epstein-Barr virus (EBV) and to expedite the entry of EBV into cells." (PMID 28520715, 2017). "CR1 is associated with the pathogenesis caused by SARS-CoV, adenoviruses and other viral infections such as HIV and HCV." (PMID 28520715, 2017). "CR1/2 deficient mice had increased numbers of macrophages and IL-1β levels in the heart, indicating that CR1/2 signaling also decreases this key proinflammatory response in the heart following viral infection." (PMID 23675015, 2007). "Determination of the expression of CR1 may be of value as an additional rapid tool in the aetiological diagnosis, bacterial or viral infection, of CAP." (PMID 16433910, 2006). "Based on these findings, we suggest that determination of the expression of CR1 on neutrophils may be of value as an additional rapid tool in the aetiological diagnosis, bacterial or viral infection, of CAP." (PMID 16433910, 2006). "The average expression levels of CR1 and CR3 on neutrophils in bacterial infections were over threefold and twofold higher, respectively, compared with viral infections and controls." (PMID 22536142, 2012). "CR1 and FcγRII were downregulated, while CR3 and FcγRI were upregulated in viral infections." (PMID 22536142, 2012).
COVID-19 (8 papers, 2022 to 2025). A disease caused by infection with severe acute respiratory syndrome coronavirus 2. "Further analysis of gene importance across the four models revealed that the top four hub genes in COVID-19 were CR1, TNFRSF10C, TAP2, and TGFBI, while the top four hub genes in SS-KCS were CR1, IL13, TAP2, and IL1R2." (PMID 40149556, 2025). "Regarding the status and severity of COVID-19, CR1 was significantly upregulated in COVID-19 patients, whereas TAP2 exhibited higher expression in healthy individuals." (PMID 40149556, 2025). "A decrease in CR1 levels was also found in patients with COVID-19 in intensive care units, along with hyperactivation of the complement system, which contributes to immune disorders during SARS-CoV-2 infection." (PMID 40149556, 2025). "However, several previous studies have reported contrasting findings regarding CR1 expression in COVID-19 patients compared to our results." (PMID 40149556, 2025). "To further elucidate the role of hub genes in the interaction between COVID-19 and SS-KCS, we performed a Pearson correlation analysis to assess the correlation between CR1, TAP2, and various immune cells." (PMID 40149556, 2025). "After a multifaceted evaluation using four mainstream machine-learning diagnostic predictors, the most accurate and sensitive random forest model identified CR1 and TAP2 as the common hub genes of COVID-19 and SS-KCS." (PMID 40149556, 2025). "The intersection of the top-ranked genes in the two diseases identified CR1 and TAP2 as shared hub genes, suggesting their potential role in linking COVID-19 and SS-KCS." (PMID 40149556, 2025). "Together with the clinical information on COVID-19, the expression of CR1 and TAP2 was significantly correlated with the status and severity of COVID-19." (PMID 40149556, 2025). "C Expression patterns varied across disease severity levels: CR1 showed the highest expression in severe COVID-19 cases and the lowest in healthy individuals, while TAP2 was most highly expressed in healthy samples and lowest in mild COVID-19 cases." (PMID 40149556, 2025). "Individual NET-specific/related biomarkers were featured in single expression graphs, where plasma phospholipase (PLC1 and PLCγ), CAS1, and PDA4 were significantly upregulated in Long-COVID, while NFkB, CR1, C3 and SLPG were depressed, compared to severe COVID-19." (PMID 37301958, 2023). "Concentrations of select chemokines (CXCL8, CXCL10, CCL2, CCL3, CCR1) and complement factors (C2, C9, CFD, C4BPA, C5AR1, CR1) were examined at mRNA and protein levels with regard to a COVID-19 course (ICU vs. non-ICU group) and CMV status at different time intervals." (PMID 36232655, 2022). "Moreover, while we confirmed the association between immune cell proportions and hub genes, we did not investigate the specific mechanisms through which CR1 and TAP2 mediate the link between COVID-19 and SS-KCS, warranting further investigation." (PMID 40149556, 2025).